IL6 (interleukin 6)
Diseases named in the same sentence as IL6 in open-access papers (continued):
Sharing a sentence is not in itself a finding about the gene and the disease.
Peri-Implantitis (continued). "In peri-implantitis, the major sources of IL-6 are macrophages, which secrete IL-6 in response to specific microbial molecules through pathogen-associated molecular patterns (PAMPs) and serve a pro-inflammatory purpose." (PMID 37232785, 2023). "This suggests that LMT-28 can be used to treat bone resorption in peri-implantitis, which is also a type of inflammation with increased IL-6 level." (PMID 36643585, 2023). "Contrariwise, two studies observed higher IL-6 levels and lower levels of IL-10 in peri-implantitis in comparison to healthy individuals." (PMID 37355561, 2023). "In peri-implantitis, however, the concentrations of IL-6 in peri-implant cervical fluid (PICF) are more substantial." (PMID 37232785, 2023). "Recent studies have shown that patients with peri-implantitis have increased expression ofpro-inflammatory cytokines, such as IL-6 and STAT-3." (PMID 37822839, 2023). "Otherwise, increasing IL-6 levels are regarded as one of the main factors for the progression of peri-implantitis, and are difficult to keep under control with treatment." (PMID 37232785, 2023). "In the gingival crevicular fluid of patients with peri-implantitis, a variety of inflammatory cytokines are elevated, such as IL-1, IL-6, prostaglandins, and metalloproteinases." (PMID 36643585, 2023). "This study revealed that sIL-6R levels in PICF from peri-implantitis sites were significantly higher in clinical studies and that Clys induced IL-6 production in HGFs in vitro." (PMID 36834667, 2023). "Similar effects can be found in our study, in which LMT-28 reduced the expression level of IL-6 in a T2DM rat model with peri-implantitis." (PMID 36643585, 2023). "Collectively, these results suggest that the lower IL-10 levels in peri-implantitis individuals result in higher IL-6 cytokines levels potentially promoting a destructive inflammatory response around dental implants." (PMID 37355561, 2023). "The present case-control study evaluated the gene expression of AhR, IL-22, and IL-6 in the peri-implant tissues of healthy and peri-implantitis patients." (PMID 35742682, 2022). "The highest levels of gene expression of the AhR-1 transcription factor and the IL-6 cytokine were found in the peri-implantitis group compared to the healthy group (p = 0.024 and p = 0.001, respectively)." (PMID 35742682, 2022). "The aim of the present case control study was to investigate the levels of gene expression of Ahr, IL-22, and IL-6 in the peri-implant soft tissues of peri-implantitis and healthy patients." (PMID 35742682, 2022). "Otherwise, a systematic review concluded that the IL-1β, IL-6, IL-17, and TNF-α were the most frequently reported pro-inflammatory mediators associated with peri-implantitis." (PMID 36233685, 2022). "In conclusion, higher gene expression levels for AhR and IL-6 were detected in the soft tissues of peri-implantitis patients." (PMID 35742682, 2022). "The analysis of IL-6 gene expression in peri-implant tissues with peri-implantitis revealed the presence of increased levels of this cytokine compared to healthy tissues." (PMID 35742682, 2022). "Apart from clinical and microbiological factors, future research should also focus on inflammatory markers such as IL-1β, IL-6 and IL-8 to identify the benefit of use of probiotics in the treatment of peri-implantitis." (PMID 34412595, 2021). "Yaghobee et al21 reported a significant difference in the IL-6 level in the gingival crevicular fluid in peri-implantitis and healthy implants and between peri-implantitis and healthy teeth." (PMID 35919677, 2021). "The hub gene IL-6 is a cytokine that stimulates immune response and is upregulated in peri-implantitis." (PMID 34931168, 2021). "Based on their results, there was no clear evidence to support the use of salivary biomarkers (IL-6, IL-1β) in peri-implantitis detection." (PMID 32349296, 2020).
Peri-Implantitis (continued). "Comparison of IL-6 level in PISF samples collected from healthy implants and those with peri-implantitis, showed that diseased sites exhibited significantly higher IL-6 levels." (PMID 33081038, 2020). "As a critical stimulator of alveolar bone resorption, IL6 can intensify local inflammatory process and aggravate peri-implantitis." (PMID 31623650, 2019). "IL6 is a proinflammatory cytokine produced by many cells in response to LPS from peri-implantitis pathogens, and it can promote the proliferation and activation of different immune cells, subsequently stimulating bone resorption potently." (PMID 31623650, 2019). "This preclinical study therefore advocates that neutralizing antibodies be further tested against IL1β, IL6, or TNFα in clinical settings for managing the aseptic loosening of orthopedic prostheses and oral peri-implantitis." (PMID 30619321, 2018). "Most studies focused on peri-implantitis and evaluated serological markers such as C-reactive protein and cytokines (IL-6, IL-1β, IL-17, tumour necrosis factor-α), along with haematological parameters including neutrophils, haemoglobin, platelets, and lymphocytes." (PMID 41301163, 2025). "In conclusion, our study demonstrates that after three months of therapy, there was a significant reduction in the expression of cytokines in the peri-implant crevicular fluid of patients with peri-implant mucositis (IL-17A and TNF-α) and peri-implantitis (IL -1β, IL-6, and TNF-α)." (PMID 39860346, 2025). "Peri-implantitis is characterized by chronic inflammation around dental implants driven by bacterial plaque accumulation, which triggers an immune cascade involving proinflammatory cytokines, such as IL-6 and TNF-α, to combat infection and tissue damage." (PMID 40959363, 2025). "For example, higher IL-6 concentrations have been detected in the peri-implant crevicular fluid of not-infected patients carrying dental implants and presenting peri-implantitis as compared to individuals with peri-mucositis or showing no clinical signs of inflammation." (PMID 38790226, 2024). "Other cytokines found in peri-implantitis include IL-4, IL-6,IL-8, IL-10, IL-12, and IL-17." (PMID 39195095, 2024). "Previous studies have shown higher levels of IL-6 in the PICF from peri-implantitis sites." (PMID 36834667, 2023). "Additionally, contrary to IL-6, IL-1β levels are lower in peri-implantitis than in peri-implant mucositis, highlighting other possible factors contributing to bone resorptions." (PMID 37232785, 2023). "Furthermore, a classification model picked up biomarkers such as Peptostreptococcaceae XIG-1, Treponema, IL-6, and IL-17A to distinguish healthy implants from peri-implantitis." (PMID 36233685, 2022). "Higher levels of gene expression of AhR and IL-6 were detected in peri-implantitis tissues." (PMID 35742682, 2022). "Additionally, qRT-PCR results showed that compared with group C, the mRNA expression level of inflammatory cytokines (IL-6 and IL-8) rose significantly in group L (P < 0.01), indicating the successful establishment of a peri-implantitis model." (PMID 36123683, 2022). "Finally, the potential target genes, namely, IL-6, TLR4, FN1, IL-1β, CXCL8, MMP-9, and SPP1, were found to be associated with peri-implantitis, and our results were consistent with those of previous studies." (PMID 34931168, 2021). "A local increase in proinflammatory cytokines (e.g., IL-6 and IL-10) in the crevicular fluid has been reported for peri-implantitis, which may plausibly have systemic effects." (PMID 34054959, 2021). "Similarly, high concentration of interleukin-6 (IL-6) appears in peri-implantitis cases which was correlated with the active phase of bone resorption." (PMID 34579704, 2021). "Furthermore, levels of IL-6 in whole saliva samples were significantly higher in patients with peri-implantitis than healthy controls." (PMID 33081038, 2020).
Peri-Implantitis (continued). "Certain key virulent attributes of peri-implantitis pathogens, such as lipopolysaccharide (LPS), can stimulate host cells in gingival and osseous tissues to overexpress proinflammatory cytokines including interleukin-6 (IL6)." (PMID 31623650, 2019). "Raised IL-6 in the peri-implant crevicular fluid has been proposed as a marker of peri-implantitis." (PMID 31275749, 2019). "Given that IL-6 is a typical inflammation-related factor produced by gingival fibroblasts and other cells that construct peri-implant tissues, sIL-6R, its receptor, may be involved in the pathology of peri-implantitis via various inflammatory cascades." (PMID 36834667, 2023). "Another two systemic reviews presented that pro-inflammatory cytokines in PICF, such as IL-1β, TNF, and IL-6, were significantly elevated in peri-implantitis and could be used as adjunct tools to clinical parameters to differentiate healthy implants from peri-implantitis." (PMID 36233685, 2022). "Similarly, peri-implantitis may influence the systemic status through inflammatory cytokines such as IL-1, IL-6, and IL-10 and matrix metalloproteinases." (PMID 34054959, 2021). "The results of this study provide significant insights into the roles of IL-6, IL-10, and TNF-α in peri-implantitis, addressing their controversial status as biomarkers." (PMID 40959363, 2025). "This prospective cross-sectional study demonstrated that IL-6, IL-10, and TNF-α levels in PICF were significantly elevated in periodontally healthy patients with peri-implantitis compared to those with healthy-periodontal implants." (PMID 40959363, 2025). "The selection of IL-6, IL-10, and TNF-α in this study was driven by their controversial roles in peri-implantitis." (PMID 40959363, 2025). "The PI, probing depth, and IL-6, IL-10, and TNF-α levels were significantly higher in the peri-implantitis group, with large effect sizes indicating substantial biological differences between the groups." (PMID 40959363, 2025). "Among DM patients with peri-implantitis, adjunctive ICG-PDT and MB-PDT demonstrated comparable outcomes in terms of peri implant clinical and pro-inflammatory characteristics (IL-6 and TNF-α) than MD alone." (PMID 39882195, 2024). "In the qualitative analysis, higher IL-6 levels in PICF and saliva of individuals with mucositis and peri-implantitis in comparison to health individuals were observed." (PMID 37355561, 2023). "The peri-implantitis model showed bone resorption and a two- to three-fold increase in inflammatory cytokines TNF-αand IL-6." (PMID 36768829, 2023). "Three studies also showed higher IL-6 and IL-10 levels in PICF of individuals with peri-implantitis in comparison with healthy individuals." (PMID 37355561, 2023). "As with other chronic inflammatory diseases, peri-implantitis progression is due to inflammatory cytokines such as IL-1β, TNF-α, and IL-6." (PMID 36768829, 2023). "In this study, pro-inflammatory cytokines of IL-1β, IL-6, IL-17A, and TNF-α were significantly higher in peri-implantitis than those in healthy implants, and this result is consistent with another study." (PMID 36233685, 2022). "In the same individual, peri-implantitis sites harbored more abundance of Treponema, Peptostreptococcaceae XIG-1, Porphyromonas, and Lachnospiraceae G-8, as well as cytokines of IL-6, IL-17A, G-CSF, RANTES, and IL-1β, than healthy implants sites." (PMID 36233685, 2022). "The genera of Peptostreptococcaceae XIG-1, Treponema, Porphyromonas, and Lachnospiraceae G-8, as well as the cytokines of IL-17A, IL-6, IL-15, G-CSF, RANTES, and IL-1β were significantly higher in peri-implantitis than healthy implants." (PMID 36233685, 2022). "The intersecting genes, including IL6, TLR4, FN1, IL1β, CXCL8, MMP9, and SPP1, were revealed as potential genetic biomarkers and target genes of peri-implantitis." (PMID 34931168, 2021). "In the present study, our results showed that the proinflammatory cytokines IL-6, IL-1β, and CXCL8 were upregulated in peri-implantitis." (PMID 34931168, 2021).
Peri-Implantitis (continued). "The expression levels of other pro-inflammatory factors, such as IL-1β, Il-6, IL-8, and TNF-α, were also higher in the GCF from peri-implantitis sites than in the GCF from healthy sites." (PMID 32760399, 2020). "According to the results, IL-1β, IL-6, and TNF-α, levels were significantly higher in mucositis and peri-implantitis than in healthy implants." (PMID 33291232, 2020). "Exploration of available transcriptomic datasets revealed IL-6, NFKB1, and PIK3CG expression along with the IL-17 signaling pathway as top candidate molecular linkage mechanisms between peri-implantitis and T2DM." (PMID 31275749, 2019). "Among these top 20 hub genes, three genes (IL6, NFKB1, and PIK3CG) were common to peri-implantitis and T2DM, thus can be regarded as the potential cross-talk genes." (PMID 31275749, 2019). "As expected, the presence of inflammatory cytokines and chemokines, particularly IL1B, IL6, its signal transducer IL6ST, and CXCL2, was clearly observed at the mRNA level in the peri-implantitis affected samples." (PMID 31242601, 2019). "Three common or cross-talk genes; IL-6, NFKB1, and PIK3CG, were noted among the top 20 hub genes in the PPI networks of T2DM and peri-implantitis." (PMID 31275749, 2019). "Three hub genes (IL-6, NFKB1, and PIK3CG) had the highest degree in PPI networks of both peri-implantitis and T2DM." (PMID 31275749, 2019). "The significant elevations in IL-6, IL-10, and TNF-α levels in the peri-implantitis group compared to those in the healthy implant group, as observed in this study, can be attributed to the heightened inflammatory response characteristic of peri-implantitis." (PMID 40959363, 2025). "Thus, pro-inflammatory cytokines such as IL-6 and STAT-3 are oftenexpressed in the tissue of patients with peri-implantitis, highlighting the importance of preventing chronic inflammation in implant patients." (PMID 37822839, 2023). "In peri-implantitis, TNF-α, IL-1α, and IL-6 are significantly upregulated." (PMID 36768829, 2023). "Among these genes, IL-6 and TLR4 showed the highest node degrees, suggesting that they may play important roles in peri-implantitis." (PMID 34931168, 2021). "This study provides supportive evidence that IL6, TLR4, FN1, IL1β, CXCL8, MMP9, and SPP1 might be used as potential target biomarkers for peri-implantitis which may provide further therapeutic potentials for peri-implantitis." (PMID 34931168, 2021). "We found that IL-6, TLR4, FN1, IL-1β, CXCL8, MMP-9, and SPP1 might be used as potential biomarkers for the diagnosis of peri-implantitis." (PMID 34931168, 2021). "Due to the heterogeneity in lipid A structure, LPS from some pathogens in peri-implantitis can interact with TLR2 and subsequently activate TLR2 downstream pathways, contributing to the production of numerous proinflammatory cytokines, including IL6." (PMID 31623650, 2019). "This study investigated the roles of interleukin-6 (IL-6), interleukin-10 (IL-10), and tumor necrosis factor-alpha (TNF-α) in peri-implantitis by comparing their levels in peri-implant crevicular fluid (PICF) between healthy implants and peri-implantitis groups." (PMID 40959363, 2025). "In agreement, lower proinflammatory cytokines (IL-1β and IL-6) and RANKL/OPG ratio were observed in peri-implant mucositis individuals in comparison to peri-implantitis individuals; this could be due to the lower peri-implant mucositis severity compared to peri-implantitis." (PMID 37355561, 2023). "IL-1β (p < 0.01), IL-6 (p < 0.01), IL-10 (p < 0.05) and TNF-α (p < 0.01) are significantly higher at the sites with peri-implantitis compared to healthy peri-implant tissue, while IL-8 did not increase significantly." (PMID 25888355, 2015). "In this study, it was found that IL-1β (p < 0.01), IL-6 (p < 0.01), IL-10 (p < 0.05) and TNF-α (p < 0.01) were significantly increased at the sites with peri-implantitis, while IL-8 was not." (PMID 25888355, 2015).
Peri-Implantitis (continued). "The results showed that the levels of IL-1β, IL-6, IL-10, and RANKL/OPG are not balanced in peri-implant disease, suggesting that these mediators are involved in the host osteo-immunoinflammatory response related to peri-implantitis." (PMID 37355561, 2023). "This study evaluated the presence of cytokines (IL-1β, IL-2, IL-4, IL-6, MCP-1, MIP-1α, MIP-1β, and TNF-α) and human herpesvirus (HSV1, HSV2, EBV, CMV, VZV, HHV6, HHV7, and HHV8) in saliva samples taken from subjects with and without peri-implantitis." (PMID 30158834, 2018). "During the treatment of peri-implant mucositis and peri-implantitis there were minimal effects of non-surgical treatment alone on the investigated inflammatory biomarkers (IL-4, IL-10, and IL-12, TNF-a, RANKL, OPG IL-1β, IL-6, TNF-α, MCP-1/CCL2, MIP-1α/CCL3, IFN-γ, MMP-8, sRANKL, OPG and G-CSF)." (PMID 36360962, 2022).